SMAD7 (SMAD family member 7)
Diseases named in the same sentence as SMAD7 in open-access papers (continued):
Sharing a sentence is not in itself a finding about the gene and the disease.
pulmonary fibrosis (continued). "FOXO3 directly bound to SPON1 and its promoter, promoted the formation of SPON1 circRNA, inhibited the nuclear translocation of Smad3 through interaction with Smad3 and sponge Smad7 as the targeted miRNAs to promote Smad7 expression, and ultimately inhibited the progression of pulmonary fibrosis." (PMID 37416778, 2023). "Over-expression of miR-21 has been demonstrated in the lungs of patients with IPF and in animal models of lung fibrosis, suggesting it may function via reduction of Smad7, a downstream inhibitor of TGF-beta signaling." (PMID 37344825, 2023). "In addition, the role of miR-21as a regulator of Smad7 expression in the lung fibrosis was reported, too." (PMID 35743055, 2022). "In a model of bleomycin-induced lung fibrosis, Smad7 gene transfer attenuated fibrogenic activity." (PMID 34905511, 2022). "Two independent reports demonstrate a role for miR-877 as a tumor suppressor in renal cell carcinoma by targeting eukaryotic elongation factor-2 kinase (eEF2K), and in myofibroblast differentiation and bleomycin-induced lung fibrosis by targeting targets Smad7." (PMID 30029522, 2018). "Our data demonstrated that miR-877-3p may promote pulmonary fibrosis by down-regulating the expression of Smad7, which is reported to serve as an inhibitor in pulmonary fibrosis." (PMID 27444321, 2016). "Although the expression of Smad7 mRNA was not changed significantly, these results indicated that the interaction of miR-877-3p and Smad7 may play an important role in the development of pulmonary fibrosis." (PMID 27444321, 2016). "In the mice, overexpression Smad7 was first reported to prevent bleomycin-induced lung fibrosis in an adenovirus-mediated gene transfer model, suggesting that Smad7 may have applicability in the treatment of pulmonary fibrosis." (PMID 22204639, 2011). "Article: Lee C-M, He C-H, Park JW, Lee JH, Kamle S, Ma B, Akosman B, Cotez R, Chen E, Zhou Y, Herzog EL, Ryu C, Peng X, Rosas IO, Poli S, Bostwick CF, Choi AM, Elias JA, Lee CG (2019 May 13) Chitinase 1 regulates pulmonary fibrosis by modulating TGF-β/SMAD7 pathway via TGFBRAP1 and FOXO3." (PMID 37037591, 2023). "This indicated that up-regulation of Smad7 may contribute to the inhibition of lung fibrosis." (PMID 27444321, 2016). "However, Smad7, which have been shown to be a miR-21 target in pulmonary fibrosis, does not appear to be implicated in our culture system, since we registered no significant regulation of Smad7 expression during EMT." (PMID 23441172, 2013). "It promotes the degradation of methylated inhibitory Smad7 by Set9, thus facilitating bleomycin-induced and Ad-TGF-β-induced pulmonary fibrosis." (PMID 40901482, 2025). "Numerous studies on treatment for idiopathic pulmonary fibrosis (IPF) focus on inhibiting the TGF-β pathway, including antagonizing TGF-β, inhibiting Smad2/3 phosphorylation, and activating Smad7." (PMID 39026235, 2024). "IL-7 and IFN-γ induce Smad7 expression through the JAK-STAT pathway, inhibiting TGF-β signal transduction and mitigating bleomycin-induced pulmonary fibrosis." (PMID 39026235, 2024). "Smad7 is a regulator of TGF-β1 signaling and a cross-mediating factor of TGF-β1 signaling, thereby playing an important role in the progression of pulmonary fibrosis." (PMID 37416778, 2023). "low level of SMAD7 in turn accelerated the phosphorylation of SMAD2/3 to promote the proliferation, migration and transition of fibroblasts, thereby exacerbating pulmonary fibrosis." (PMID 34093874, 2021). "IL-7 induces Smad7 expression via the JAK-STAT pathway and inhibits bleomycin-induced pulmonary fibrosis by inhibiting TGF-β signaling." (PMID 34198949, 2021). "The miR-21 can regulate the expression of inhibitory Smad/Smad7 signaling pathway via TGF-β1, promote the activation of fibroblasts, and lead to pulmonary fibrosis." (PMID 33817326, 2021).
pulmonary fibrosis (continued). "In animal models of pulmonary fibrosis, administering antibodies to TGF-β or blocking signal transduction modulated by active TGF-β by over-expressing the inhibitory Smad-7 blocks fibrosis." (PMID 16606467, 2006). "For instance, Smurf1 and Smurf2, which facilitate the ubiquitin-dependent degradation of the unmethylated Smad7-TβR complex, reduce TGF-βsignaling and may thus mitigate pulmonary fibrosis." (PMID 40901482, 2025). "By targeting SMAD7, a negative regulator of the TGFβ signalling pathway, miR-182-5p amplifies TGFβ induced epithelial to mesenchymal transition (EMT) and metastasis of cancer cells while inhibition of miR-182-5p reduces pulmonary fibrosis." (PMID 38920689, 2024). "Furthermore, a recent animal study also showed that upregulating Smad-7 inhibits the TGF-β1/Smad signalling pathway and alleviates pulmonary fibrosis." (PMID 38398472, 2024). "To determine whether CAT played an important role in the TGF-β signaling pathway in pulmonary fibrosis, we measured the protein expression levels of TGF-β1, Smad2/3, p-Smad2, p-Smad3, Smad7 as well as Snail." (PMID 35685407, 2022). "Because miR-21-induced Smad7 downregulation contributes to bleomycin-induced pulmonary fibrosis (BLM fibrosis), miR-21 induction in mesenchymal cells may promote the TGF-β gene response by suppressing Smad7." (PMID 27171163, 2016). "Moreover, the glycolytic enzyme PKM2 tetramer enhances TGF-β1 signaling through direct binding of Smad7 to its MH2 structural domain, which interferes with the interaction between Smad7 and the TGF-β type I receptor (TβR1), reduces TβR1 ubiquitination, stabilizes TβR1, and affects lung fibrosis." (PMID 41300843, 2025). "In addition, the elevated SRPX2 would inhibit the expression of AP1, and then attenuated SMAD7 expression, forming a positive feedback loop to enhance TGF-β/SMADs signaling, which could finally promote FMT and exacerbate pulmonary fibrosis." (PMID 34093874, 2021). "SMAD4 and SMAD7 have a regulating activity to SMAD2/3 and play a significant regulatory role in pathophysiological processes such as skin healing and pulmonary fibrosis; however, NAM showed no obvious effect on the protein expression of SMAD4 and SMAD7 at 28 dpi." (PMID 38973179, 2024). "MiR-21 could control pathways such as the TGF-β1 signaling pathway by targeting SMAD7 and SPRY1 or by inhibiting PTEN, which is a known negative regulator of lung fibrosis." (PMID 30658565, 2019).
hepatocellular carcinoma (38 papers, 2013 to 2025). A malignant tumor that arises from hepatocytes. "In this study, high level of TGF‐β1 was observed in the biopsies of cancer patients with hepatoma, which was associated with Smad3 hyperactivation but Smad7 reduction in the TME." (PMID 34514726, 2021). "Previous studies have revealed that SMAD7 acts as a tumor suppressor in a variety of cancers, including gastric cancer, bladder cancer, and hepatocellular carcinoma." (PMID 35912252, 2022). "Our study demonstrated that JPHYD inhibits the proliferation and invasion of hepatocellular carcinoma cells by regulating miR-21-5p/Smad7 and the expression of EMT-related proteins." (PMID 35518787, 2022). "LncRNAs SNHG6 and SNAI3-AS1 bind to UPF1 and recruit it to the mRNA that codes for the protein known as small mothers against decapentaplegic homolog 7 (SMAD7) and enables the degradation of SMAD7 mRNA in hepatocellular carcinoma via the NMD process." (PMID 36010595, 2022). "Previous studies identified miR-21-3p target genes: in ovarian cells it targets NAV3, a known tumor suppressor; in hepatocellular carcinoma, it targets SMAD7, an inhibitor of the TGFβ pathway; and in ESCC, it targets TRAF4." (PMID 34797887, 2021). "A recent study showed that A1BG-AS1 interacts with miR-216a and SMAD7 in suppressing hepatocellular carcinoma proliferation, both partners having an important role in the positive regulation of osteoblastic differentiation in mice." (PMID 34088266, 2021). "Overexpression of has-miR-216a/217 activates the PI3K/Akt and TGF-β signaling pathways by targeting PTEN and SMAD7 in human hepatocellular carcinoma cells." (PMID 27384321, 2016). "In hepatocellular carcinoma, miR-21-3p regulates both TGFβ and Hippo signalling via SMAD7 and YAP1." (PMID 38920689, 2024). "Additionally, the miR-21-3p can also promote hepatocellular carcinoma progression via SMAD7 signal pathway." (PMID 36233353, 2022). "Interestingly, miR-216a/217-induced EMT promoted drug resistance via targeting phosphatase and tensin homolog (PTEN) and mothers against decapentaplegic homolog 7 (SMAD7) in hepatocellular carcinoma." (PMID 25638153, 2015). "In another study, it was shown in hepatocellular carcinoma (HCC) that downregulation of UPF1, due to promoter hypermethylation, inhibited NMD and upregulated expression of SMAD7." (PMID 36833284, 2023). "Tanshinone IIA mediated Smad7 cooperated with YAP to induce apoptosis and inhibit cell and migration by inhibiting TGF‐β signaling pathway in hepatocellular carcinoma cells." (PMID 37382248, 2023). "SNAI3-AS1 can bind to up-frameshift protein 1, regulate Smad7 expression, and activate the TGF-β/Smad pathway to induce EMT in hepatocellular carcinoma." (PMID 34288803, 2021). "Furthermore, SMAD7 was included as one of a target of miR-106b-5p and miR-17-5p, based on reports which SMAD7 might influence cancer cell proliferation and metastasis in hepatocellular carcinoma." (PMID 30989460, 2019). "In hepatocellular cancer, miR-21 was predicted to regulate “immune response” by targeting CD69, STAT3, CCL20 and SMAD7, in which STAT3 and SMAD7 are important signaling molecules for immune response." (PMID 24278370, 2013). "We found that JPHYD could inhibit the proliferation, invasion, and migration of hepatocellular carcinoma cells and JPHYD decreased the level of N-cadherin, Snail, Vimentin, Smad3, and Zeb1 and increased E-cadherin and Smad7 proteins." (PMID 35518787, 2022). "XIST was shown to exhibit tumor suppressive properties in hepatocellular carcinoma (HCC) by acting as a miRNA decoy for tumor suppressor genes, SMAD7 (SMAD family member 7) and PTEN, by sponging miR-92b and miR-181a, respectively, and suppressing cell proliferation, metastasis, and invasion." (PMID 29702599, 2018).
lung carcinoma (38 papers, 2010 to 2025). "Collectively, our results demonstrate that the expression of nuclear ProT is associated with the suppression of EMT via enhancing Smad7 acetylation, which impacts lung cancer progression." (PMID 40259641, 2025). "Our findings identified the oncogenic role of PRMT5 in human lung cancer and elucidated a novel mechanism underlying the modulation of the Smad7‐gp130‐STAT3 axis by PRMT5 in those cancer types with aberrantly hyperactivation of STAT3." (PMID 34026434, 2021). "Furthermore, the changes in SMAD7 expression were associated with the malignant transformation of bronchial epithelial cells and the development of lung cancer." (PMID 25295107, 2014). "Nuclear prothymosin α inhibits epithelial‐mesenchymal transition (EMT) in lung cancer by increasing Smad7 acetylation and competing with Smad2 for binding to SNAI1, TWIST1, and ZEB1 promoters." (PMID 40259641, 2025). "Next, we investigated the roles of aberrant nuclear ProT expression and decreased Smad7 in EMT‐related lung cancer progression." (PMID 40259641, 2025). "Nevertheless, significant discrepancies were observed in PFS and DMFS between patients exhibiting low and high Smad7 expression, suggesting a correlation between decreased Smad7 expression and lung cancer progression and poor patient survival." (PMID 40259641, 2025). "For instance, depletion of SMAD7 in lung cancer cells markedly increased transwell migration and invasion." (PMID 36550779, 2023). "At present, there are few studies on the role of SMAD7 in the occurrence, development, invasion and metastasis of lung cancer." (PMID 34254453, 2021). "It has been previously reported that SMAD7 expression is reduced in cisplatin‐resistant lung cancer A549 cell lines." (PMID 34254453, 2021). "Studies have been reported that, in lung cancer, miR-21-5p promotes cell malignant behaviors by impairing SMAD7 expression." (PMID 34889164, 2021). "Recent studies have shown that SMAD7 is present in common malignancies and acts as a tumor suppressor, including lung cancer, liver cancer, gastric cancer, bladder cancer, triple negative breast cancer, and osteosarcoma." (PMID 32899503, 2020). "The candidate miRNA identified, miR-21-5p is well-known to function as a tumor promoter and directly targets SMAD7 in lung cancer." (PMID 33147570, 2020). "We propose that one of the mechanisms for fucoidan-mediated inhibition of lung cancer in vivo and in vitro depends on promoting the ubiquitination and degradation of TGFRs via Smurf2/Smad7." (PMID 25149540, 2014). "Consequently, high expression of Snail, Twist1, and ZEB1 in conjunction with low expression of Smad7 and nuclear ProT was correlated with a poor prognosis in patients with lung cancer." (PMID 40259641, 2025). "In addition to SMAD3, SMAD4 and SMAD7 are also involved in a range of biological behaviours in lung cancer." (PMID 37685308, 2023). "Luo found that overexpression of SMAD7 overexpression increased lung cancer incidence." (PMID 35912252, 2022). "miRNA‐21‐5p may promote cell proliferation, migration and invasion by spoiling SMAD7 expression in lung cancer cells." (PMID 34254453, 2021). "In addition, we found that SMAD7 inhibited lung cancer cell proliferation and miR‐21‐5p mimic damaged the inhibitory effect of SMAD7." (PMID 34254453, 2021). "We analyzed SMAD7 expression in lung cancer tissues using the starBase and GEPIA databases." (PMID 34254453, 2021). "We have recently reported that AA is a Smad7 agonist and NG is a Smad3 inhibitor in lung carcinoma." (PMID 34514726, 2021). "The downregulation of Smad7 promotes lung cancer metastasis under TGF-β1 signaling activation." (PMID 34912481, 2021). "In summary, miRNA‐21‐5p affects the migration and proliferation of lung cancer H1299 cells through targeted regulation of SMAD7 expression in lung cancer cells, suggesting that miRNA‐21‐5p is a potential target, which can be used for the intervention and prevention of the lung cancer process." (PMID 34254453, 2021).
lung carcinoma (continued). "In addition, according to the survival curves defined by high and low expression of SMAD7 in lung cancer patients, it was found that a high expression level of SMAD7 had an important effect on the overall survival of patients." (PMID 34254453, 2021). "To determine whether SMAD7 was regulated by miR-182 endogenously, we analysed miR-182 expression levels in the breast and lung cancer cell lines and assessed the effects of miR-182 overexpression or inhibition in these cells." (PMID 27996004, 2016). "Here, we examined whether Smurf2 and/or Smad7 are involved in the processing step of the fucoidan-mediated UPP degradation of TGFR in lung cancer cells." (PMID 25149540, 2014). "In the current study, we postulated that caspase‐3 may cleave the NLS of ProT, leading to its relocation from the nucleus to the cytoplasm and consequently impeding the regulatory role of ProT in mediating transcriptional repression of EMT in lung cancer via Smad7." (PMID 40259641, 2025). "Interestingly, it can also act as an anti-tumor immunotherapeutic agent thanks to its inductive effect on Smad7 in combination with naringenin (Smad3 inhibitor), which increases the ability of NK cells to inhibit the progression of invasive melanoma and lung carcinoma in animal models and in vivo." (PMID 38610995, 2024). "Thus, we speculate that the suppression of SMAD7 expression resulted in activation of the TGF-β1 signaling pathway leading to enhancement of metastasis in lung cancer." (PMID 37462692, 2023). "Like in mESC, overexpression of Smad7 could enhance STAT3 activation in lung carcinoma A549 cells." (PMID 34026434, 2021). "Furthermore, Smad6 and Smad7 correlate with poor prognosis in lung cancer and gastric carcinomas." (PMID 23049692, 2012). "LETS1 blocks the inhibitory effect of SMAD7 on TGFβR1 by increasing the expression of NR4A1, a protein involved in SMAD7 polyubiquitination and degradation, facilitating TGFβ-induced EMT and cellular migration in breast and lung cancer." (PMID 39937018, 2025). "REGγ (a proteasome activator) can activate SMAD7 through degradation of TGF-β signalling and promote lung cancer metastasis." (PMID 37685308, 2023). "Studies related to lung cancer have found that the expressions of SMAD6, SMAD7, and SMAD9 in SMADs are downregulated in lung cancer and significantly correlated with the prognosis of patients." (PMID 36969909, 2023). "Next, we analysed the RNA expression levels of the TGFβ target genes p21, PAI1, SMAD7, and TGFB1 following SHP099 treatment in KRAS mutant lung cancer cell lines." (PMID 38102334, 2023). "In lung cancer, the protein arginine methyltransferase 5 (PRMT5) binds to SMAD7 and methylates it on arginine-57, enhancing the binding of SMAD7 to the IL-6 co-receptor gp130, thereby ensuring potent activation of STAT3, which in turn promotes tumour cell proliferation and progression." (PMID 37685308, 2023). "SMAD7 affects the progression of lung cancer mainly by influencing EMT, a complex nonlinear biological process." (PMID 37685308, 2023). "It functions as an oncogene through silencing many tumor suppressor genes such as PDCD4, PTEN, SMAD7, HIF-1α, and others, all of which play key roles in different aspects of lung cancer development including cell cycle, apoptosis, drug resistance, and distant metastasis." (PMID 34885115, 2021). "In addition, fucoidan reduces tumor size in LLC1-xenograft male C57BL/6 mice and decreases tumor growth by modulating the TGFR/Smad7/Smurf2-dependent axis, leading to TGFR protein degradation and inhibition of lung cancer cell progression in vitro and in vivo." (PMID 31041568, 2019). "This study was identified a novel mechanism for the anti-tumor activity of fucoidan, namely decreasing tumor growth by modulating the TGFR/Smad7/Smurf2-dependent axis, leading to TGFR protein degradation and inhibition of lung cancer cell progression in vitro and in vivo." (PMID 31041568, 2019).
lung carcinoma (continued). "Thus, our clinical data further confirmed that LKB1 loss increased the DNA methylation and expression level of ALKBH5, which resulting in the demethylation of m6A modification on SOX2, SMAD7, and MYC, and maintaining their expression for KRAS mutant lung cancer." (PMID 34016959, 2021). "Also, the application of this approach to a lung cancer data set identifies focal amplification regions that contain known oncogenes, though these regions are not reported using a recent CNAs detecting algorithm GISTIC: SMAD7 (chr18q21.1) and FGF10 (chr5p12)." (PMID 21569311, 2011). "However, the contribution of Smad7 specifically in lung epithelium to lung cancer has not been characterized." (PMID 20405019, 2010). "In addition, although CAV1, SMAD7, BMP2, EDN1, and CXCL12 were not significantly different in the prognostic analysis in our study, they also play important roles in the occurrence and development of lung cancer." (PMID 34820377, 2021).